HMGB1 (high mobility group box 1)
Diseases named in the same sentence as HMGB1 in open-access papers (continued):
Sharing a sentence is not in itself a finding about the gene and the disease.
pulmonary fibrosis (continued). "The potential pathogenic role of HMGB1 in IPF has been supported by experimental animal models, indicating that anti-HMGB1 antibodies can prevent bleomycin-induced pulmonary fibrosis." (PMID 36110858, 2022). "Our previous studies demonstrated that Nrf2 attenuated the epithelial mesenchymal transition process in pulmonary fibrosis through inhibition of HMGB1 pathway." (PMID 36699071, 2022). "The role of TLR4-activating DAMPs in pulmonary fibrosis has been further evaluated with high-mobility group box1 (HMGB1), a potent inducer of TLR4 in pulmonary fibrosis." (PMID 34258628, 2021). "On the other hand, studies on pulmonary fibrosis showed that downregulation of HMGB1 is necessary for effective antioxidant activity of Nrf2, which plays a pivotal role in HO-1 production." (PMID 33440644, 2021). "In our previous reports, we suggested that HMGB1 was associated with fD reductions in mice models of COPD and lung fibrosis due to alveolar structural changes caused by inflammation." (PMID 34257627, 2021). "Glycyrrhizin can inhibit the progression of bleomycin induced lung fibrosis in rats by inhibiting HMGB1." (PMID 32117622, 2020). "Inhibiting HMGB1 prevented the development of pulmonary fibrosis in rats induced by bleomycin, also inhibited the EMT progress in NSCLC cells and weakened their invasion and migration abilities." (PMID 32117622, 2020). "In fibroblasts, HMGB1 significantly increases collagen deposition and plays an important role in pulmonary fibrosis." (PMID 31481891, 2019). "Other researchers have shown that increased expression of HMGB1 in the airway epithelium leads to pulmonary fibrosis as well as epithelial mesenchymal transition via TGF-β." (PMID 30728013, 2019). "In the present study, AP-1 and NF-κB participated in the development of pulmonary fibrosis, and this progress was regulated by the phosphorylation and expression of ROS, HMGB1, and MAPKs." (PMID 29849916, 2018). "Serum HMGB1 level was significantly higher in patients with AE-FIP than in those with stable idiopathic pulmonary fibrosis (16.4±13.5 vs 5.7±2.6 ng/ml, respectively; p = 0.003)." (PMID 29795561, 2018). "Our present data implied that gefitinib inhibited pulmonary fibrosis in vivo through HMGB1/NOXs-ROS/EGFR-ERK/JNK/P38 pathways." (PMID 29849916, 2018). "High-mobility group box 1 (HMGB1) is a ubiquitous nuclear protein that acts as a crucial factor in acute lung injury progression and pulmonary fibrosis." (PMID 29670673, 2018). "Pulmonary receptor for advanced glycation end-products (RAGE), a well-characterized cell surface receptor of HMGB1, was down-regulated after asbestos injury in a mouse model of pulmonary fibrosis." (PMID 28348451, 2017). "Hamada and colleagues demonstrated that HMGB1 protein was predominantly detected in fibrotic lesions of lung tissues in patients with idiopathic pulmonary fibrosis and was increased in bleomycin-treated mouse lung tissues compared to that in control tissues." (PMID 23617783, 2013). "Some researchers have previously reported that high-mobility group box 1 (HMGB1) was correlated with pulmonary fibrosis." (PMID 23617783, 2013). "Protocatechuic aldehyde reduces pulmonary fibrosis via inhibiting the HMGB1/RAGE pathway." (PMID 39008169, 2024). "However, in the context of abnormal tissue repair in pulmonary fibrosis, excessive HMGB1 activates fibroblasts and enhances endothelial cell proliferation, thereby exacerbating pulmonary fibrosis." (PMID 39199705, 2024). "We speculate that glycyrrhizic acid can also inhibit the expression of HMGB1 in silica-induced pulmonary fibrosis." (PMID 35886594, 2022). "Anti-HMGB1 antibody significantly attenuated lung fibrosis in a mouse model." (PMID 34258628, 2021). "The present study suggested that gefitinib could alleviate lung fibrosis through the HMGB1/NOXs-ROS/EGFR-MAPKs-AP-1/NF-κB signal in bleomycin-induced pulmonary fibrosis." (PMID 29849916, 2018).
pulmonary fibrosis (continued). "Published studies have reported that abnormal HMGB-1 activation is involved in the development of pulmonary fibrosis (PF), and could serve as novel diagnosis or treatment biomarkers for PF." (PMID 30558126, 2018). "In summary, we comprehensively investigated the role of the molecule HMGB1, the involvement of oxidation-antioxidant unbalance, and the related molecule transduction mechanism downstream of gefitinib treatment in bleomycin-induced pulmonary fibrosis." (PMID 29849916, 2018). "First, we concentrated on the role of HMGB1 in the development of pulmonary fibrosis." (PMID 29849916, 2018). "This study demonstrated the anti-fibrotic effects of ASV in lung fibrosis, which may be due to its regulation on HMGB1 release and ECM production, suggesting an attractive pharmacological tool for the treatment of PF." (PMID 28848434, 2017). "HMGB1 may play a crucial role in fibrotic diseases and thus become a promising target for treating lung fibrosis." (PMID 28039939, 2017). "Given the importance of HMGB1 with regard to pulmonary fibrosis, we hypothesized that HMGB1 may also directly influence lung fibroblast activation and it is still obscure." (PMID 25692286, 2015). "However, it is reported that HMGB1 plays an important role in many tissues fibrosis, such as pulmonary fibrosis, cystic fibrosis, renal fibrosis and so on." (PMID 24912759, 2014). "In addition, there are also some data which indicated that HMGB1 played critical roles in pulmonary fibrosis, cystic fibrosis and renal fibrosis." (PMID 24912759, 2014). "Some researchers have previously reported that HMGB1 was correlated with pulmonary fibrosis." (PMID 23617783, 2013). "In addition, anti-HMGB1 antibodies can significantly reduce pulmonary fibrosis in animal models." (PMID 36110858, 2022). "HMGB1 may also be a potential target for treating inflammation and improving pulmonary fibrosis." (PMID 36110858, 2022). "Genetic or pharmacological inhibition of RIPK3 reduces HMGB1 release in pulmonary fibrosis and subarachnoid hemorrhage models, and reduced HMGB1 signaling could indirectly contribute to improved functional outcome in CCI because of its role in IL-1 beta production via toll-like receptor signaling." (PMID 34753914, 2021). "In patients with PF, HMGB1 reflected the entity of pulmonary impairment and represented an independent biomarker for the progression of lung function, which could be used for monitoring lung fibrosis." (PMID 28039939, 2017). "Administration of anti-HMGB1 antibody or ethyl pyruvate inhibits inflammation, apoptosis, and fibrosis, thus alleviating BLM-induced lung fibrosis." (PMID 39008169, 2024). "In idiopathic pulmonary fibrosis (IPF) and hypersensitivity pneumonitis (HP), the HMGB1 levels in bronchoalveolar lavage fluid (BALF) are increased compared to the control group." (PMID 39008169, 2024). "Mechanistically, HMGB1 activated the PI3K/AKT/mTOR signaling pathway to increase cell proliferation and migration, promoting endothelial-mesenchymal transition in pulmonary fibrosis." (PMID 37945340, 2023). "HMGB1 released after lung injury induces apoptosis resistance of fibroblasts via activation of TLR4, leading to persistent pulmonary fibrosis." (PMID 35111363, 2022). "For example, when combined with RAGE, HMGB1 and S100A8/A9 are suggested to play a role in pulmonary fibrosis." (PMID 36110858, 2022). "The nucleotide-binding oligomerization domain-like receptor 3 (NLRP3) inflammasome and HMGB1/toll-like receptor 4 (TLR4) play vital roles in inflammation and pulmonary fibrosis, and NLRP3 is a key regulator of HMGB1 release." (PMID 31481891, 2019). "Raltegravir ameliorated pulmonary fibrosis by reducing the pathology score, collagen deposition, and expression of α-smooth muscle actin, NLRP3, HMGB1, TLR4, inhibitor of kappa B, p-NF-κB, HIF-1α, collagen I, and collagen III." (PMID 31481891, 2019).
pulmonary fibrosis (continued). "In the present study, we demonstrated the relationship between HMGB1 and α-SMA and the therapeutic effect of gefitinib in bleomycin-induced pulmonary fibrosis in mice." (PMID 29849916, 2018). "In this study, we tried to reveal the model of action between high-mobility group box 1 (HMGB1) and α-smooth muscle actin (α-SMA) and the protective role of gefitinib in pulmonary fibrosis induced by the administration of bleomycin aerosol in mice." (PMID 29849916, 2018). "This is in agreement with studies showing overexpression of HMGB1 and RAGE in other fibrotic disorders such as systemic sclerosis fibrotic skin lesions, idiopathic pulmonary fibrosis, and bleomycin-induced lung fibrosis." (PMID 21365018, 2011). "Moreover, PM2.5 has been reported to drive inflammatory reactions and promote pulmonary fibrosis through downregulation of PPAR-γ and concurrent activation of the HMGB1/NLRP3 inflammasome pathway." (PMID 41322289, 2025). "A growing body of evidence indicates that NETs and their individual components contribute significantly to the progression of pulmonary fibrosis, including the DNA core strands themselves, histones, components of neutrophil granules (e.g., MPO, NE), HMGB1, and others." (PMID 40001601, 2025). "Inhibition of HMGB1 expression promoted the nuclear translocation of nuclear factor erythroid 2-related factor 2 (NRF2) and enhanced HO-1 levels, thereby reducing NLRP3 expression and partially reversing lung fibrosis." (PMID 40688353, 2025). "Itraconazole may counteract lung fibrosis induced by BLM through decreasing oxidative stress, modulating the HMGB1, TLR4 NLRP3 and NF-κB signaling, and affecting the balance between autophagy and apoptosis." (PMID 39008169, 2024). "Other drugs that inhibit HMGB1 levels and hence inhibit BLM-induced lung fibrosis include thrombomodulin, fatty acid, nitrogenes, astragaloside IV, Yupingfeng, pulmonary rehabilitation mixture, dioscin, simvastatin, and some fragments of the depolymerized heparins." (PMID 39008169, 2024). "Based on Nrf2 knockout mice, we verified that Nrf2 activation remarkably downregulated the expression of HMGB1, inhibited the TGF-β-induced epithelial-mesenchymal transition and reactive oxygen species generation, subsequently ameliorated the development of pulmonary fibrosis." (PMID 36699071, 2022). "HMGB1 may induce apoptosis resistance of fibroblasts via activating Toll like receptor 4 (TLR4) by NF-κB and PI3K/Akt signaling, leading to persistent pulmonary fibrosis." (PMID 35111363, 2022). "HMGB1 is a highly conserved non-histone chromosome binding protein, which is closely related to a variety of lung diseases, including pneumonia, tuberculosis, chronic obstructive pulmonary disease, pulmonary fibrosis, and lung transplantation." (PMID 32116668, 2019). "On the other hand, some studies have suggested that the elevated HMGB-1 contributes to pulmonary fibrosis by activating the epithelial-to-mesenchymal transition (EMT) signaling pathway, which might be another route for the development of silica-induced pulmonary fibrosis." (PMID 30558126, 2018). "The detailed mode of action between HMGB1 and α-SMA in pulmonary fibrosis, however, has not yet been fully interpreted." (PMID 29849916, 2018).
ovarian cancer (51 papers, 2014 to 2026). A primary or metastatic malignant neoplasm involving the ovary. "In line with our data, others described HMGB1 deficiency in tumor cells to occur in subsets of colorectal and ovarian cancers." (PMID 40804938, 2025). "Recent studies have linked HMGB1 to the promotion of malignant behaviors in various cancers, including liver cancer, ovarian cancer, and non-small cell lung cancer, through the modulation of mitochondrial function, EMT, autophagy, and other pathways." (PMID 40975711, 2025). "Induced autophagy releases HMGB1, a prototypical damage-associated molecular pattern protein that enhances treatment resistance in lung cancer, colorectal cancer and ovarian cancer." (PMID 41151762, 2025). "Zhang and colleagues It was found that HMGB1 regulates autophagy through NAC1 (ovarian cancer-associated gene 1) in ovarian cancer cells." (PMID 38601753, 2024). "Reducing NAC1 activity leads to lower HMGB1 levels and diminished autophagy, causing reduced growth and heightened apoptosis in ovarian cancer cells triggered by cisplatin, thereby increasing the cancer’s vulnerability to cisplatin." (PMID 38601753, 2024). "High serum HMGB1 concentrations and low serum sRAGE levels were associated with ovarian cancer as compared to benign cases and healthy controls." (PMID 37894448, 2023). "HMGB1 has been repeatedly proposed as a diagnostic and prognostic biomarker for human ovarian cancer." (PMID 32867128, 2020). "Downregulation of SIRT1 also led to decreased migration and angiogenesis of ovarian cancer cells by repressing HMGB1, and was associated with decreased OS in serous ovarian cancer." (PMID 31113446, 2019). "In human epithelial ovarian cancer, the protein HMGB1, together with tumour-associated macrophages, enhances lymphangiogenesis." (PMID 26682011, 2016). "However, we obtained the opposite result for ovarian cancer, where high HMGB1 expression is linked with poor prognosis of OS and PFS." (PMID 36230798, 2022). "HMGB1 over-expression is associated to prostate and ovary cancers: in this work, using a proteomic approach, we aimed to discover new protein interactions that might contribute to understand the oncogenic function of HMGB1 in cancers models." (PMID 34572914, 2021). "Of note, HDAC inhibitors caused HMGB1 release from the PDX ovarian cancer isolate “Spiky”." (PMID 29137331, 2017). "To determine whether the HMGB1 expression was associated with patient survival, we stained a primary (Nottingham) cohort comprised of 194 ovarian cancer cases using immunohistochemistry with a rabbit monoclonal antibody specific for endogenous HMGB1." (PMID 29254158, 2017). "Although beyond the scope of this study, it will be important to determine whether expression of HMGB1 in ovarian cancer is associated with other markers of autophagy including LC3B and Beclin-1." (PMID 29254158, 2017). "Numerous cancer cells, including osteosarcoma, lung adenocarcinoma, neuroblastoma and ovarian cancer, have been shown to be protected against multiple chemotherapeutics, such as DOX, cisplatin and etoposide, by autophagy-associated HMGB1." (PMID 41151762, 2025). "Taxol has been shown to induce the release of DAMPs such as calreticulin, ATP and HMGB1 in ovarian cancer cells." (PMID 40369535, 2025). "The extracellular levels of ATP and HMGB1 in the culture supernatants of treated ovarian cancer cells were evaluated in this study." (PMID 41362788, 2025). "Cell-cell communication analysis identified the HMGB1-HAVCR2 ligand-receptor pair mediating communication from ovarian cancer cells to terminally exhausted CD8 + T cells." (PMID 41240232, 2025). "The high-mobility group box protein 1 (HMGB1) is a known nucleotide excision repair (NER) cofactor, and its family member HMGB3 has been implicated in chemoresistance in ovarian cancer." (PMID 41009989, 2025).
ovarian cancer (continued). "High Mobility Group Box 1 (HMGB1) was identified as a key ligand expressed in ovarian cancer cells influencing the IL32 expression in terminally exhausted CD8 + T cells." (PMID 41240232, 2025). "In macrophages co-cultured with ovarian cancer, AS-IV suppresses the elevated levels of HmgB1 and TLR4, further supporting the notion that HmgB1 can promote M2 macrophages, whereas AS-IV has the opposite effect." (PMID 39064966, 2024). "For instance, C-MYC inhibits ferroptosis induced HMGB1 release mediated by NCOA4 in ovarian cancer cells." (PMID 39192972, 2024). "The ratio of both markers, HMGB1/sRAGE, differentiated even better between women with ovarian cancer and healthy or benign controls." (PMID 37894448, 2023). "Future validation studies are warranted to confirm the potential applicability of HMGB1 and sRAGE in ovarian cancer diagnostics." (PMID 37894448, 2023). "Although this study lacks validation in an independent cohort, HMGB1 and the HMGB1/sRAGE ratio clearly seem to be promising and easily accessible biomarkers for the detection of ovarian cancer and possibly even for benign ovarian diseases." (PMID 37894448, 2023). "In this respect, more studies with a prospective design and a variety of clinical characteristics will be needed to further evaluate possible applicability of HMGB1, sRAGE and the HMGB1/sRAGE ratio in ovarian cancer." (PMID 37894448, 2023). "As part of a prognostic model based on differentially expressed genes, HMGB1 showed promising results in the prognosis of ovarian cancer." (PMID 37894448, 2023). "To date, only a few other studies have examined HMGB1 in the diagnosis or prognosis of ovarian cancer, and blood-based studies are scarce." (PMID 37894448, 2023). "In several studies, HMGB1 expression in tissue samples of ovarian cancer was predictive for poor survival of patients with ovarian cancer." (PMID 37894448, 2023). "To extend the number of targets detected in the Y2H interactomes, we also carried out a HMGB1-interactome analysis approach based on immunoprecipitation (IP) and mass spectrometry (MS) in prostate and ovary cancer cell lines." (PMID 37110415, 2023). "In a study by Li and Wei, the expression of HMGB1, together with the expression of BRCA1 and P62, was associated with drug resistance and sensitivity to chemotherapy in ovarian cancer." (PMID 37894448, 2023). "In conclusion, HMGB1 and sRAGE are potential candidates for the development of assays for early diagnosis of ovarian cancer and warrant inclusion in further validation studies." (PMID 37894448, 2023). "The expression of HMGB1 in tissues and serum of ovarian cancer patients was higher than that of benign tumor or normal control group." (PMID 36081910, 2022). "In this experiment, we found that in ferroptosis-activated ovarian cancer cells, HMGB1 and PGE2 contents released outside the cell membrane obviously increased." (PMID 36552889, 2022). "HMGB1 was assayed since necrosis played a part in ultrasonic chemosensitization on resistant ovarian cancer cells COC1/DDP." (PMID 36388164, 2022). "Immunohistochemical staining and flow cytometry analysis of tumor tissues showed that in C-MYC knock-down ovarian cancer samples, the HMGB1 contents in the extracellular situation were significantly increased." (PMID 36552889, 2022). "In conclusion, the analysis of the HMGB1 interactomes in prostate and ovary cancer cells reveals new connections of HMGB1 functions to RNA processing and ribosome biogenesis through interactions with components of the NuRD complex, THOC complex and septins." (PMID 34572914, 2021). "High expression of HMGB1 has been related to cisplatin resistance and downregulation of HMGB1 re-sensitizes ovarian cancer cells to carboplatin." (PMID 32867128, 2020). "It has been reported that SIRT1 induces HMGB1 expression, thereby modulating ovarian cancer behaviors." (PMID 33343352, 2020).